MYC (MYC proto-oncogene, bHLH transcription factor)
Diseases named in the same sentence as MYC in open-access papers (continued):
Sharing a sentence is not in itself a finding about the gene and the disease.
tumor (continued). "In other words, deregulated MYC can bind MAX and alter normal ongoing gene expression programs to impose a tumor-specific transcription profile." (PMID 30054853, 2018). "This cooperativity is at least in part based on suppression of RAS-induced cellular senescence by MYC and block of MYC-induced apoptosis by RAS – thereby canceling out two main barriers against tumor development." (PMID 30526305, 2018). "This concept is in accordance with the experimental demonstration of anti-tumor effects of D2-HG, which decreases the stability of MYC/CEBPA transcripts via N6-methyladenosine RNA modification and thereby inhibits tumor cell survival and proliferation." (PMID 30416682, 2018). "Genetic perturbation of this enhancer-docking site in tumor cells reduces CTCF binding, super-enhancer interaction, MYC gene expression, and cell proliferation." (PMID 29641996, 2018). "We here provide mechanistic evidence demonstrating regulation of MYC splicing by SHQ1 as an important event involved in T-cell leukemogenesis, thus revealing the tumor-supporting role of SHQ1 in human cancers that links SHQ1 to RNA splicing and leukemogenesis." (PMID 30323192, 2018). "Among the 10 amplification-based oncogenes, we identified that six genes (MDM2, MYC, MYCL, MYCN, NKX2-1, and SKP2) were amplified and overexpressed in ≥10 tumor samples." (PMID 28377632, 2017). "YAP1 mRNA and protein levels were higher in PTC tumor tissues than in control tissues, and correlated positively with the levels of proliferation-related genes (KI67 and c-MYC)." (PMID 28036290, 2017). "In summary, we described a molecular mechanism whereby ID1 regulated Wnt/ β-catenin/c-MYC pathway, which in turn activated the PPP, thus encouraging tumor proliferation and oxaliplatin chemoresistance in HCC." (PMID 29169374, 2017). "Synergistic responses were observed with downregulation of MYC and MCL1 expression levels, and significant suppression of tumor cell growth in xenograft mouse models." (PMID 28362357, 2017). "Deregulated expression of the MYC family of transcription factors, particularly c-MYC and MYCN genes, has been found in many of these neoplasms, and their expression levels are often correlated with poor prognosis." (PMID 28333115, 2017). "Forced expression of activated STAT3 in fibroblast cell lines resulted in 3-6 fold up-regulation of MYC, CCND1 (coding for cyclin D1) and BCL2L1 (BCL-XL) mRNA, and permitted tumor formation in nude mice." (PMID 29207662, 2017). "MYC and HIF-1α are known to cooperatively activate glycolysis to generate adequate energy for tumor cells, resulting in chemo-resistance through the upregulation of many genes relevant to glucose metabolism." (PMID 28055963, 2017). "Of TCGA KIRC tumours (n=525), 87, 13 and 31% had VHL inactivation, MYC activation and CDKN2A deletion, respectively." (PMID 28593993, 2017). "PIM2 promotes tumor survival mainly through phosphorylation of the pro-apoptotic BH3-only protein BAD, as well as through regulation of MYC activity, and Cap-dependent protein translation." (PMID 28561737, 2017). "Our mouse models of pRCC and ccRCC faithfully recapitulate the genomics of human RCC although the incidence of ccRCC tumours that have coincident VHL and CDKN2A inactivation, along with MYC activation is only ∼6%." (PMID 28593993, 2017).
tumor (continued). "Recently, a high-resolution analysis of somatic copy-number alterations (SCNAs) from 3131 cancer specimens revealed that amplification of the human c-MYC gene occurs in most types of malignancies, underscoring the critical role of c-MYC in tumor pathogenesis." (PMID 28076844, 2017). "In these conditions, both HIF-1 and MYC cooperate to further enhance their effects on glycolytic enzymes including LDH-A, resulting in glycolysis and the Warburg effect often seen in tumor cells." (PMID 28362357, 2017). "Both patients developed refractory diseases within 1 year after diagnosis that were accompanied by MYC and BCL2 rearrangements in their tumor cells." (PMID 28055963, 2017). "N-MYC (subsequently demonstrated also for c-MYC) was found to directly bind to two E-box sequences in the GCN5 promoter, thereby increasing its transcription in tumor cells." (PMID 28505071, 2017). "Aberrant PI3K signaling thus results in an increased half-life of MYC proteins, suggesting that restoration of GSK-3β activity using inhibitors directed toward PI3K signaling will disrupt tumor growth." (PMID 28333115, 2017). "Although a few sensitive tumours belonged to the ECM/EMT group, those were showing similarities with the ASCL2/MYC samples (subgroup A)." (PMID 28186126, 2017). "Increased levels of c-MYC phosphorylation on Serine62 and c-MYC activity were observed in the skin lesions of the B56αhm/hm mice." (PMID 29190822, 2017). "RT-qPCR and Western blot analysis of tumor cells derived from EμSRα-tTA;tet-o-MYC transgenic mice indicate that DNMT3B expression levels were elevated in MYC-driven T-ALL compared to normal spleen from wild-type C57BL/6J mice." (PMID 29100357, 2017). "Comparison of MYC expression levels between total tumor and ANCT tissues showed a significant up-regulation in tumor tissues (P=0.02)." (PMID 28480695, 2017). "MYC is the most prominent Notch target gene in NOTCH1-dependent T-ALL, and its contribution to T-ALL cell proliferation and tumor maintenance is well established." (PMID 29023469, 2017). "In summary, we conclude that the ESCC microenvironment promotes tumor angiogenesis by coercing NECs to change toward TECs, with the activation of JAK/STAT3/c-MYC signaling pathway." (PMID 29088816, 2017). "MYC and VEGFA levels were also increased in metastatic colon cancer cohort compared with primary tumor, similar to RBP4." (PMID 28689994, 2017). "A second observation was that MYC reduces pten mRNA levels, suggesting that protein kinase B (AKT) pathway activation downstream of MYC is responsible of tumor progression." (PMID 28930163, 2017). "TC68 cells, overexpressing concomitantly MYC, p-AKT and HIF-1α proteins (the DIPG tumor with the bar), close to the protein profile of SF188 cells, were showing an equivalent sensitivity as SF188 cells." (PMID 29069732, 2017). "HUWE1 is an E3 ubiquitin ligase that controls the stability of MCL1, MYC and MYCN functions which would suggest a tumour‐suppressive role." (PMID 28003334, 2017). "“Double-hit score,” representing IHC-based evaluation of tumor cell expression of BCL2 and MYC, showed that 10/76 (13%) cases were positive for both MYC and BCL2." (PMID 28302137, 2017).
tumor (continued). "Remarkably, MAT1A overexpression, or c-MYC, MAFG, or c-MAF inhibition in tumor cells dramatically inhibited their in vitro and in vivo growth." (PMID 28422055, 2017). "While under non-malignant conditions an equilibrium exists that is defined by the relative abundance of MYC and MXD proteins, the constitutively elevated expression of MYC shifts the balance toward activation in tumor cells." (PMID 28505071, 2017). "MYC, which is located directly upstream of FAM83H, is often amplified at the DNA copy number level in many tumor types." (PMID 28078827, 2017). "Most known oncogenes (e.g. EGFR, FGFR1, MYC, ERBB2) or tumor suppressors (e.g. CDKN2A, NOTCH1) were detected to reside within the focal SCNA regions." (PMID 29348864, 2017). "We examined the mechanism of MYC down regulation by VLX600 and found that it occurred at the level of decreased mRNA stability and up-regulation of tumor suppressive let-7a family and miR-34a-5p miRNAs." (PMID 29163823, 2017). "By contrast, up-regulation of c-MYC, MAFG, and c-MAF or attenuation of MATa1 expression by knock-down triggered increased tumor cell growth and invasion in vivo." (PMID 28422055, 2017). "Recent evidence suggests that MYC regulates the expression of CD47 and PD-L1, two important immune checkpoint proteins on the tumor cell surface." (PMID 28333115, 2017). "For example, BIN1, as a tumor suppressor, interacts with MYC (v-myc avian myelocytomatosis viral oncogene homolog) and inhibits its proliferative activity." (PMID 28257090, 2017). "Recently, MCT1 was shown to be a MYC target and inhibition of MCT1 resulted in intracellular lactate accumulation in tumor cells, and eventual cell death." (PMID 28362357, 2017). "We also observed that the Shannon diversity indices for c-MYC and FGFR1 copy number variation were correlated, again suggesting that the degree of ITH in a tumor is an intrinsic feature of that tumor." (PMID 29228597, 2017). "Alterations in the expression of c-MYC and E2F1 affect liver cell ploidy during hepatic growth—after birth and before tumor onset." (PMID 28422055, 2017). "The study also identified MYC, HNF4A and TGFB1 as top upstream regulators correlating to tumor tissue content." (PMID 28445515, 2017). "Expression levels of MYC and CCND1 were significantly elevated in tumor tissues than those in normal tissues (2.80-fold with MYC probe #202431, p=4.0x10-14; 1.91-fold with CCND1 probe #208711, p=8.96x10-7; and 2.11-fold with CCND1 probe #208712, p=8.79x10-9)." (PMID 29245969, 2017). "Next, we combined the immunohistochemical staining patterns of MYC, MINA53 and Ki67 with the histomorphological pRCC tumor subtype." (PMID 29180625, 2017). "A link between LDH-A and c-MYC has been verified, and knockdown of LDH-A can significantly diminish tumor growth in a mouse model." (PMID 27399091, 2016). "Although the baseline tumour also had amplified MYC and CCND1, these were distinct events with breakpoints different than those observed in the surgical tumour." (PMID 27502118, 2016). "In addition, several cell cycle-related genes whose protein products initiate DNA replication are transcriptional MYC targets, which could explain why deregulated DNA synthesis, chromosomal abnormalities, and genomic instability frequently occurs in human tumor cells containing activated MYC." (PMID 27313991, 2016). "Our data on CDK9 identifies that CDK9 inhibition is an important mechanism the anti-tumor effect of dinaciclib and establishes CDK9 as a potential therapeutic target for MYC driven TNBC." (PMID 27486754, 2016). "Recently, exposure of enzalutamide-resistant mCRPC cells to BETi (JQ1 and OTX015) resulted in attenuation of AR target genes (FKBP5, KLK3, ERG, and MYC) and AR-v7 expression as well as decreased CRPC cell proliferation in vitro and tumor growth in vivo." (PMID 27651838, 2016).
tumor (continued). "A previous study showed that c-MYC together with HIF-1α induced the overexpression of VEGF, leading to tumor angiogenesis." (PMID 27483433, 2016). "RHOA, SMAD2, SMAD4, SMAD5, SMAD6, BMPR1A, SMAD7 and MYC-, which thereby emerge as candidate genes to play an important role in CRC tumor metastasis." (PMID 27662660, 2016). "Here, the authors show that c-MYC requires the chromatin reader BPTF to activate its transcriptional program and promote tumour development in vivo, suggesting that BPTF is a potential target for cancer therapy." (PMID 26729287, 2016). "The qRT-PCR based panel of MYC, MYCN, CCND1, CCND2, EGFR and FNDC3A was successful in detecting neoplasia with an overall accuracy of 54 % in S-CRN compared to that of 29 % in UC neoplastic samples." (PMID 27080994, 2016). "We observed that miR-203 overexpression modulated expression of EMT and tumor stemness factors including suppression of ZEB2, N-cadherin, NANOG, c-MYC, and BMI1 as well as induced E-cadherin expression." (PMID 27589832, 2016). "MYC amplification was identified in 1 sample (CDC2) and up-regulation in all 4 tumor samples analyzed (adjusted p-value < 0.001)." (PMID 27144525, 2016). "Immunohistochemistry (IHC) of MYC, BCL2 and BCL6 was performed on tumor samples from 114 patients with PCNS-DLBCL." (PMID 27286976, 2016). "For instance, the let-7 family of miRNAs can target oncogenes, such as MYC and RAS family members, to inhibit tumor growth." (PMID 27957388, 2016). "Previous studies found that there is a significant enrichment of H3K4Me3 modification in the TSS regions of MYC and EGFR genes in many tumor cells." (PMID 27087825, 2016). "Reported mechanisms include overexpression or mutations in PSMB5 (the proteasomal target of BTZ), P-glycoprotein expression (efflux pump), microenvironmental upregulation of IL-6, IGF-1, or tumor upregulation of HSP90, PI3K, MYC, and IGF-1." (PMID 26254279, 2015). "Induction of MYC translocation led to T-ALL, with withdrawal of 4-hydroxytamoxifen resulting in complete tumor regression in nearly 75% of fish." (PMID 25884214, 2015). "In these studies, increased DKC1 expression was related to markers of tumour proliferation, like high TERC, MKI67 and MYC levels." (PMID 26366868, 2015). "The only RNA replacement clinical trial to date began in April 2013 as a strategy to deliver miR-34, a tumor-suppressive miRNA that regulates expression of BCL-2 and MYC, to patients with liver-based cancers." (PMID 25849966, 2015). "Blocking NFκB in c-MYC and PIM2 overexpressing cells induces apoptosis in vitro and inhibits growth in a tumour graft model." (PMID 26643319, 2015). "For instance, the let-7 family of miRs tends to act as tumor suppressors by targeting a number of pro-survival molecules such as RAS, BCL-XL, and MYC." (PMID 25750899, 2015). "In BL, the conjunction of MYC activation, EBV infection, or other cellular gene alterations can drive B-cell to uncontrolled proliferation and tumour formation." (PMID 26089910, 2015). "Copy number alterations of MYC (8q24.21), FHIT (3p14.2), WDR60 (7q36.3), COL4A2 (13q34), NFATC1 (18q23), and NCOA3 (20q12) were analyzed in six matched tumor and normal tissue pairs (268–1, 271–1, 272–2, 301–1, 685–1 and 685–2)." (PMID 26360582, 2015).
tumor (continued). "GISTIC analysis defined significant common regions of amplification and deletion that harbour multiple oncogenes (for example, MYC and CCND1) and tumour suppressors (for example, SMAD4 and CDKN2A)." (PMID 25855536, 2015). "Greater proteomic variability was observed between human tumor tissue samples than in culture, however significant differences in HNRNPA2/B1 (p = 0.005) and MYC (p = 0.013) were still detected between MYC+ and MYC− tissues." (PMID 25970789, 2015). "We further show that this upregulation of MYC is mediated by BRD4 regulation of the MYC gene and that combining a BRD4 inhibitor with everolimus leads to enhanced tumor growth inhibition in vitro and in vivo." (PMID 25537515, 2015). "Akt/mTOR pathway was highly activated in CRPC and p-Akt was reported to target and stimulate the expression of tumorigenic factors like c-MYC, SOX2, OCT4 and eventually robust tumor growth." (PMID 26317998, 2015). "The secretion of IL-10 by immune and malignant cells, as induced by the E6 protein of human papilloma virus type 16 or 18, contributed to tumor progression by upregulating CIP2A and MYC." (PMID 25015035, 2014). "Pathway and network analyses suggested that NKX3.1 actuates a cellular reprogramming toward luminal cell differentiation characterized by suppression of pro-oncogenic c-MYC and interferon-STAT signaling and activation of tumor suppressor pathways." (PMID 25177484, 2014). "Although we have focused on functions of SIRT6 in regulating MYC and HIF, it is very likely that other roles of SIRT6 are also relevant for its tumor suppressor capacity." (PMID 25085992, 2014). "Although the post-transcriptional interplay between YY1 and c-MYC and between YY1 and HDAC2 both favour tumour progression, the former activates the fast cell cycle/pluripotency genes, and the latter represses differentiation/fast cell cycle inhibitor genes." (PMID 25115389, 2014). "In summary, the collaborations among LDHA, MYC and SIRT1 can indeed widen the window of miR-34-induced tumor suppression." (PMID 24884974, 2014). "nc886's tumor suppressive role is corroborated by the induction of well-known oncogenes such as FOS, NF-κB, and MYC upon its knockdown." (PMID 25003254, 2014). "Chromosomal abnormalities of MYC, LPL and PTEN, and aneusomy (as measured by copy number changes of the chromosome-specific CEP probes) were observed in tumour ROIs of the radical prostatectomy specimens." (PMID 24568597, 2014). "Thus, lower intestinal levels of MYC may be part of the tumor preventive mechanism of PGD2." (PMID 24729479, 2014). "HMGCR regulates the phosphorylation status of MYC, which is known as a crucial oncogene in HCC, and affects tumor growth in vitro and in vivo." (PMID 24776759, 2014). "The miR-34 family is composed of miR-34a,miR-34b and miR-34c and mediates tumour cell activities through cell cycle arrest, apoptosis or senescence, and metastasis 34–36, depending on its targets, such as the oncogenes BCL-2,c-MYC and c-MET8,10,35." (PMID 25213795, 2014). "The anti-tumor activity of AUY922 and docetaxel in vivo was investigated by treating castrated FVB mice with MYC-CaP/CR tumors." (PMID 25072314, 2014). "Downregulation of MYC transcription by BET inhibitor, JQ1 compound, resulted in significant anti-tumor activity in mouse models." (PMID 25495526, 2014). "In line with its role as a regulator of tumour cell proliferation, we discovered that cells depleted of FBXO28 downregulated genes activated by the transcription factor MYC." (PMID 23776131, 2013).